PEBP1 (phosphatidylethanolamine binding protein 1)
Diseases named in the same sentence as PEBP1 in open-access papers (continued):
Sharing a sentence is not in itself a finding about the gene and the disease.
asthma (12 papers, 2016 to 2025). "The multivariate analysis revealed that low PEBP1 levels were strongly associated with asthma and severe asthma (p < 0.001)." (PMID 40506894, 2025). "In the multivariate analysis, age, gender, BMI, and PEBP1 levels were significantly associated with asthma severity." (PMID 40506894, 2025). "Patients with PEBP1 levels <1112.0 pg/mL had a significantly higher risk of severe asthma in Model 1 (OR = 216.15, 95% CI: 1.92–215,555.09, and p < 0.05) and Model 3 (OR = 227.57, 95% CI: 2.03–210,000.33, and p < 0.05)." (PMID 40506894, 2025). "This study aims to evaluate the clinical utility of serum PEBP1 and 15-LO-1 levels, and their ratio, as potential biomarkers of asthma, and explores their association with disease severity and lung function impairment." (PMID 40506894, 2025). "This cross-sectional study investigates the relationship between ferroptosis markers, specifically PEBP1, 15-LO-1, and 15-LO-1/PEBP1 ratio, and their association with asthma and its severity." (PMID 40506894, 2025). "The role of ferroptosis in asthma, particularly through the PEBP1/15-LO-1 axis, has been implicated in linking lipid peroxidation to inflammatory pathways, offering insights into the disease’s underlying mechanisms." (PMID 40506894, 2025). "Our findings from the multivariate analysis demonstrate that low PEBP1 and high 15-LO-1 are significantly and independently associated with asthma, but only low PEBP1 is associated with severe asthma; similarly, the 15-LO-1/PEBP1 ratio showed a significant association with asthma." (PMID 40506894, 2025). "In the multivariate analysis, PEBP1 and 15-LO-1 levels were significantly associated with asthma." (PMID 40506894, 2025). "We hypothesize that the dysregulation of serum ferroptosis markers, specifically an imbalance in PEBP1 and 15-LO-1 levels, is associated not only with the presence of asthma but also with its severity." (PMID 40506894, 2025). "Additionally, a study found that PEBP1 caused the interaction between proferroptotic 15LO1 and the autophagic protein microtubule-associated light chain-3 to involve in asthma." (PMID 35635016, 2022). "The GLM plots from our study demonstrate an inverse relationship between asthma severity and PEBP1 levels, and a direct relationship between severity and 15-LO-1 levels, though the correlation strength appears moderate." (PMID 40506894, 2025). "The ferroptosis markers PEBP1 and 15-LO-1 are increasingly recognized as potential biomarkers for asthma." (PMID 40506894, 2025). "The phosphatidylethanolamine-binding protein 1 (PEBP1)/15-lipoxygenase (15-LO-1) complex, a key mediator of ferroptosis, is found to be elevated in asthma patients." (PMID 40506894, 2025). "In summary, our study contributes to the growing body of evidence that suggests a significant link between ferroptosis markers and asthma severity, highlighting the potential of PEBP1 and 15-LO-1 as biomarkers for assessing and managing asthma." (PMID 40506894, 2025). "Recent research implicates ferroptosis in asthma pathogenesis, with the PEBP1/15-LO-1 complex playing a central role." (PMID 40506894, 2025). "Patients with PEBP1 levels < 1509.8 pg/mL had markedly higher odds of asthma (OR = 416.71, 95% CI: 58.33–11,043.30, p < 0.001)." (PMID 40506894, 2025). "The significant correlations between lower PEBP1 levels, higher 15-LO-1 levels, and severe asthma highlight the potential of these markers as therapeutic targets." (PMID 40506894, 2025). "Given the intricate relationship between ferroptosis and asthma, there is a compelling need for a detailed comparative study of ferroptosis markers, specifically PEBP1 and 15-LO-1." (PMID 40506894, 2025). "Most of the current research available in the literature has focused on elucidating the role of PEBP1 and 15-LO-1 in the pathogenesis of asthma." (PMID 40506894, 2025).
asthma (continued). "Phosphatidylethanolamine-binding protein 1 (PEBP1) can promote ferroptosis in asthma, kidney injury, and brain trauma, and inhibit the metastasis of tumor cells." (PMID 39311766, 2024). "PEBP1, phosphatidylethanolamine-binding protein 1, is involved in ferroptosis in airway epithelial cells in asthma." (PMID 35222395, 2022). "A previous report found that PEBP1 expression was decreased in IgE−Fc receptor-Stimulated Mast Cells and in Peripheral Blood from Asthma Patients." (PMID 35635016, 2022). "Similarly, in the context of moderate and severe asthma, PEBP1 and 15-LO-1 demonstrated predictive performance, with AUCs of 0.847 and 0.863, respectively." (PMID 40506894, 2025). "The colocalization level of PEBP1 and 15-LO in human airway epithelial cells (HAECs) of patients with asthma is higher than that in those of the normal population, indicating the likelihood of ferroptosis in HAECs of patients with asthma." (PMID 37259023, 2023). "The 15LO1/PEBP1 pathway should be investigated as a novel asthma therapeutic target." (PMID 34762602, 2022). "Phosphatidylethanolamine-binding protein 1 (PEBP1), a scaffold protein inhibitor that binds to the two isoforms of 15-lipoxygenase (15-LO), can promote ferroptosis in asthma, kidney injury, and brain trauma." (PMID 34115610, 2021). "Youden’s index values indicate that PEBP1 and 15-LO-1 are particularly effective in discriminating between subjects with asthma and without asthma." (PMID 40506894, 2025).
colon cancer (10 papers, 2012 to 2022). "Moreover, PEBP1 is significantly associated with poor patient prognosis in stage II colon cancer patients." (PMID 34073365, 2021).
gastric adenocarcinoma (9 papers, 2012 to 2025). "Natural killer (NK) cells, both in their resting and activated states, displayed a positive correlation with the co-expression of PEBP1/STK11 across a broad spectrum of cancers, predominantly within the gastrointestinal tract (excluding CHOL and gastric adenocarcinoma (STAD))." (PMID 40806276, 2025).
liver cancer (7 papers, 2016 to 2025). An epithelial or non-epithelial malignant neoplasm that arises from the liver. "The results of TCGA database also showed that PEBP1 was low expressed in liver cancer and negatively correlated with the degree of malignancy in human liver cancer, which further manifested the important role of PEBP1 in the development of HCC." (PMID 34925691, 2021). "Subsequently, we detected and compared the expression of PEBP1, Ki67 in liver cancer, and paracarcinoma tissues." (PMID 34925691, 2021). "Identical to what have been found, the expression of PEBP1 in liver cancer tissues was much lower than that in paracarcinoma tissues." (PMID 34925691, 2021).
neuroblastoma (7 papers, 2017 to 2024). Neuroblastoma (NB) is the most common solid, extracranial childhood tumor. "Depletion of PEBP1 suppresses the neuronal differentiation of SH-SY5Y neuroblastoma cells induced by retinoid acid, while PEBP1 overexpression facilitates differentiation into neurons without retinoic acid treatment in media." (PMID 31683736, 2019). "The involvement of PEBP-1 in the MAPK signaling is well documented in the studies showing that PEBP-1 promotes neuronal differentiation by binding to c-Raf and avoiding MEK phosphorylation, both in a human neuroblastoma cell line and in adult rat hippocampal progenitor cells." (PMID 37627556, 2023).
diabetes (6 papers, 2014 to 2025). "Lower expression in patients with diabetes was evident for SCPEP1, S100A11, LEP, PEBP1, SHGB, and APOF." (PMID 37792298, 2023). "Prednisone administration or knockdown of Pebp1, highly expressed in db/db mice, alleviated hepatic injury and necroptosis induced by recombinant AAV in mice with diabetes and obesity." (PMID 37272212, 2023). "Finally, phosphatidylethanolamine binding protein 1, also known as RKIP1 appears to have an important role in the pathophysiology of diabetes." (PMID 29857581, 2018).
metastatic melanoma (6 papers, 2017 to 2023). A melanoma that has spread from its primary site to another anatomic site. "We here describe PEBP1 as a novel gene whose low expression on blood leukocytes is associated with poor survival in metastatic melanoma patients receiving DC therapy." (PMID 28978044, 2017).
brain trauma (5 papers, 2011 to 2024). "First, the PEBP1/15LOX complex in cortical and hippocampal neurons is a potential treatment target for brain trauma." (PMID 32754017, 2020). "Therefore, ferroptosis prevention in brain trauma strengthens the defense system, removes oxidized membrane lipids, prevents 15LOX/PEBP1 complex formation, and reduces the membrane lipid dioxide oxidation rate." (PMID 32754017, 2020). "One study revealed that PEBP1 acts as a switch between ferroptosis and necroptosis by inhibiting pro-necroptotic RIPK3 activity while activating 15-LOX to produce pro-ferroptotic HpETE-PE signals after irradiation and brain trauma." (PMID 39286656, 2024).
diabetic nephropathy (5 papers, 2017 to 2025). "Additionally, dysregulated PEBP1 expression was also observed to contribute to Alzheimer’s disease (AD) and diabetic nephropathy." (PMID 34677480, 2021).
bladder cancer (4 papers, 2021 to 2023). "As in this biomarker discovery study, downregulated expression of PEBP1 is observed in many cancers as they progress, including bladder cancer." (PMID 37371512, 2023). "For example, in bladder cancer, low PEBP1-expressing tumors had significantly higher activity scores in the apoptosis (FDR = 3 × 10−6) and EMT (FDR = 1.2 × 10−7) pathways, compared to high-expressing BLCA tumors." (PMID 37894300, 2023). "In addition, PEBP1, also known as Raf kinase inhibitory protein (RKIP), was downregulated in sEVs of bladder cancer patients in this study." (PMID 37371512, 2023).
glioblastoma (4 papers, 2012 to 2023). The most malignant astrocytic tumor (WHO grade IV). "In addition, high PEBP1 expression was associated with a worse outcome of anti-PD-1 therapy in skin melanoma (Riaz), but was related to better anti-D-L1 therapy outcomes in glioblastoma (Zhao)." (PMID 37894300, 2023).
metastatic cancer (4 papers, 2017 to 2022). A carcinoma which has spread from the original site of growth to another anatomic site. "Specifically, reduced expression of PEBP1 is highly associated to metastatic cancers, such as prostate metaplasia." (PMID 28719635, 2017).
ovarian carcinoma (4 papers, 2008 to 2025). A malignant neoplasm originating from the surface ovarian epithelium. "Our results strongly suggest that PEBP1 variants are present in the sera and ascites of ovarian cancer patients." (PMID 18652693, 2008). "Although we cannot exclude that the presence of PEBP1 in ovarian patient fluids could result from tumor cell death and degradation, altogether our results suggest that additional variants of PEBP1 exist in ovarian cancer patient fluids." (PMID 18652693, 2008). "In conclusion, using a novel type of biotinylated recombinant antibodies that we call biobodies, we identified complement catabolitic products, EMILIN2, Von Willebrand factor and PEBP1 or a related protein, as candidate markers for ovarian carcinoma." (PMID 18652693, 2008). "This analysis generated preferential binding of anti-PEBP1 antibody to case serum with a p-value of 0.02, demonstrating that the presence of PEBP1 in serum is able to differentiate ovarian carcinoma from control sera." (PMID 18652693, 2008). "PEBP1 was detected in 29 out of 30 ascites samples and discriminated ovarian cancer sera from controls (p = 0.02)." (PMID 18652693, 2008). "Independent evidence for ovarian cancer-specific expression of PEBP1 in patient sera was found by ELISA assays and antibody arrays with anti-PEBP1 antibodies." (PMID 18652693, 2008). "PEBP1 is normally a basic cytosolic protein but our results suggest the existence in patient fluids of a soluble form of PEBP1 that is a serum marker for ovarian cancer." (PMID 18652693, 2008). "The overall comparison between case and control sera was performed on a protein array platform using anti-PEBP1 center pAb and an independent set of ovarian cancer and control sera." (PMID 18652693, 2008). "Anti-PEBP1 center pAb ranked 17 out of 338 full length antibodies and performed better than 4 out of 8 anti-CA125 mAbs in preferential binding to the serum of individual cancer patients, suggesting that PEBP1 is a marker for ovarian cancer." (PMID 18652693, 2008). "This antibody as well as two other polyclonal antibodies directed against PEBP1 N-terminal region or the whole PEBP1 protein could also detect large amounts of protein in 29 out of 30 ovarian cancer patient ascites." (PMID 18652693, 2008). "A polyclonal antibody directed against the conserved PE-binding sequence of PEBP1 could accurately (p = 0.02) discriminate between ovarian cancer and control sera on antibody arrays." (PMID 18652693, 2008). "As antibodies were commercially available, PEBP1 was further evaluated by ELISA test using an independent set of ovarian cancer ascites, by western blots on a panel of normal and tumor tissues and tumor cell lines, and by antibody arrays with a new set of case and control sera." (PMID 18652693, 2008).
prostate tumors (4 papers, 2018 to 2024). "In accordance with these findings, our analysis show that the expression of RKIP/PEBP1 was lower in metastatic tissues compared to benign and primary prostate tumor tissues." (PMID 30115852, 2018).
atherosclerosis (3 papers, 2017 to 2023). A disease characterized by the build-up of fatty material and calcium deposition in the arterial wall resulting in partial or complete occlusion of the arterial lumen. "Beside as a cytosolic protein, PEBP1 also has been shown to be secreted into circulation and participates in cardiac physiology, such as atherosclerosis." (PMID 29163033, 2017). "PEBP1 is involved in regulating endothelial cell autophagy and affects atherosclerosis." (PMID 36017103, 2022). "In addition, PEBP1 is widely expressed in several organs and could be secreted in to circulation to participate in atherosclerosis." (PMID 29163033, 2017). "The interaction of PEBP1 with PC-PLC could positively regulate PC-PLC activity, negatively regulate autophagy and participate in atherosclerosis development." (PMID 29163033, 2017).
Cerebral ischemia (3 papers, 2017 to 2023). Restriction of arterial blood supply to the brain associated with insufficient oxygenation to support the metabolic requirements of the tissue. "This study aimed to estimate the role of phosphatidylethanolamine binding protein 1 (PEBP1) in cerebral ischemia-reperfusion (I/R) injury and the underlying mechanisms." (PMID 29163033, 2017). "PEBP1 has been reported to be involved in neuronal death and inflammation following cerebral ischemia‐reperfusion injury." (PMID 37287422, 2023).
colitis (3 papers, 2019 to 2023). Inflammation of the colon. "As a master regulatory molecule of 15-LOX, it was observed that the loss of phosphatidylethanolamine-binding protein 1 (PEBP1) is beneficial to reduce colitis symptoms and accelerate mucosal recovery." (PMID 35378823, 2022).
cutaneous melanoma (3 papers, 2020 to 2023). A primary melanoma arising from atypical melanocytes in the skin. "Together, our results suggest that PEBP1 and YY1 mutations associate with the infiltration of specific immune cells in skin melanoma and uterine corpus endometrial carcinomas, respectively." (PMID 37894300, 2023). "We found a significant enrichment of Th2 cells in PEBP1 mutant skin melanomas (logFC = 0.304, p = 0.035), as well as an enrichment of B cells in YY1 WT skin melanomas (logFC = −0.56, p = 0.018)." (PMID 37894300, 2023).
depression (3 papers, 2011 to 2025). "PEBP1 has been suggested to be involved in chronic stress-induced memory impairment, MOBP has been linked to mood disorders, LTA4H to depression in women, and KCNN2 to anxiety and stress responses." (PMID 21504592, 2011).
Parkinson disease (3 papers, 2018 to 2023). A progressive degenerative disorder of the central nervous system characterized by loss of dopamine producing neurons in the substantia nigra and the presence of Lewy bodies in the substantia nigra and locus coeruleus. "Leonurine attenuates phospholipid peroxidation by preventing the assembly of the ALOX15/PEBP1 complex, thereby alleviating chronic stress‐induced Parkinson's disease susceptibility." (PMID 37622525, 2023).
renal cell carcinoma (3 papers, 2014 to 2024). "In renal cell carcinoma (RCC), circPOLR2A, regulated by YTHDF2 through m6A modification, enhances the interaction between PEBP1 and UBE3C." (PMID 39075555, 2024).
allergic asthma (2 papers, 2016 to 2024). A asthma with a basis in a pathological type I hypersensitivity reaction. "The present MR results suggested the presence of associations between the risk of allergic asthma and BAX, CASP3, CCND1, ICAM1, PEBP1, RAF1, and ERBB2 expression." (PMID 39769348, 2024). "Based on the inverse variance weighted method, the MR analysis provided evidence of associations between allergic asthma and BAX, CASP3, CCND1, ERBB2, ICAM1, PEBP1, and RAF1 in the blood." (PMID 39769348, 2024).
allergic disease (2 papers, 2022). An immune response that occurs following re-exposure to an innocuous antigen, and that requires the presence of existing antibodies against that antigen. "The results demonstrated that allergens can result in allergic diseases accompanied by alteration of PEBP1, HMGB1 and TLR4 levels via miR-205-5P." (PMID 35635016, 2022). "Though best known in allergy and anaphylaxis, the TME mast cells highly express immunosuppressive IL6R and ferroptosis-related signatures including PEBP1 and NCOA4." (PMID 36148946, 2022).
brain cancer (2 papers, 2018 to 2023). A primary or metastatic malignant neoplasm affecting the brain. "The most associated diseases with the TRPV2 interactome were neoplasms and diseases from the nervous system, and ABR, FGF1, KNJ10, PEBP1, PLP1, SOC3, and TRPV2 were found to be associated with brain neoplasms." (PMID 29719613, 2018). "This analysis identified neoplasms and nervous system diseases as the most associated diseases with the TRPV2 interactome, and highlighted a set of genes previously associated to brain neoplasms, such as: ABR, FGF1, KCNJ10, PEBP1, PLP1, SDC3 and TRPV2." (PMID 29719613, 2018).
cardiac hypertrophy (2 papers, 2018 to 2022). "The RKIP-induced cardiac hypertrophy and cardiac dysfunction were (partially) prevented by down-regulation of RKIP with lentiviral transduction of an miRNA targeting the RKIP (PEBP1) by RNA interference." (PMID 30687708, 2018).
Cognitive impairment (2 papers, 2017 to 2019). Abnormal cognition is characterized by deficits in thinking, reasoning, or remembering. "Downregulation of PEBP1 could be associated with cognitive impairment which has been suggested to occur under exposure to high doses of F78, 79, despite this theory still being debated." (PMID 28432311, 2017). "In addition, chronic corticosterone treatment results in cognitive impairment via the down-regulation of PEBP1 expression in the hippocampus." (PMID 31683736, 2019). "PEBP1 is involved in neuronal cell death and cognitive deficits in neurodegenerative diseases." (PMID 31683736, 2019).
Hypertension (2 papers, 2014 to 2024). The presence of chronic increased pressure in the systemic arterial system. "rs113360897, rs611251, rs11668424, rs1805419 of BAX, and rs2936839 of PEBP1 exhibited pleiotropy, wherein rs113360897, rs611251, and rs2936839 were related to red cell distribution width and inflammation in patients with non-dipper hypertension." (PMID 39769348, 2024).